CD4 (CD4 molecule)
Diseases named in the same sentence as CD4 in open-access papers (continued):
Sharing a sentence is not in itself a finding about the gene and the disease.
colitis (continued). "The family member NR4A2 also regulates immune cell function and subsequently colitis, as deletion of NR4A2 in T cells attenuates induction of Tregs and causes aberrant induction of Th1 CD4+ T cells and subsequent exacerbation of colitis." (PMID 31139192, 2019). "We evaluated the effect of MT-1303 on colitis induced by the adoptive transfer of CD4+CD45RBhigh T cells from BALB/c mice to SCID mice." (PMID 31805144, 2019). "To investigate the influence of the iron depleted diet on colitis development, we chose to study the CD4+ CD62L+ T cell transfer induced colitis model." (PMID 31276514, 2019). "In a cell transfer model of enteritis, CD4+ CD45RBhigh T cells from VDR KO mice induced more severe colitis in recombinase-activated gene (Rag) 2 KO recipient mice than CD4+ CD45RBhigh T cells from wild-type mice." (PMID 30804707, 2019). "Ileitis develops spontaneously over a period of 8–16 weeks in the heterozygous TNFΔARE mice, whereas severe colitis develops within 2–3 weeks in the CD4+ CD62L+ T cell transfer colitis under our experimental conditions." (PMID 31276514, 2019). "Western blotting analysis showed that the p-AMPK activity of colitis LP CD4+ T cells was significantly increased by AICAR treatment and significantly suppressed by C.C. treatment." (PMID 31417110, 2019). "Later, several studies using macrophage- or CD4+ cell-specific PPARγ KO mice revealed that the expression of PPARγ in macrophages or CD4+ T cells protects against colitis." (PMID 30804707, 2019). "The addition of AICAR resulted in the suppression of the frequency of IFN-γ- and IL17A-producing colitis LP CD4+ T cells." (PMID 31417110, 2019). "In contrast to the effect of AICAR on colitis LP CD4+ T cells, the addition of C.C. increased the frequency of IFN-γ-producing colitis LP CD4+ T cells as well as that of IL-17A-producing LP CD4+ T cells." (PMID 31417110, 2019). "Colitis in B6DC-LMP1/CD40 mice was accompanied by increased frequencies of LP-infiltrating IL-17+IFN-γ+ CD4+ T cells and IFN-γ+ Th1 cells, corroborating data published previously." (PMID 30653608, 2019). "In the present study, rBmaCys-treated colitis mice had elevated percentages of CD4+IL-10+ Tregs in LPMCs and CD4+ Tregs in MLNs." (PMID 31683524, 2019). "We used CD4+T cell-transfer colitis models in our in vitro and in vivo experiments, although most previous reports used colitis models in which colitis was induced by chemicals, such as DSS17–20." (PMID 31417110, 2019). "Intracellular cytokine staining of colonic CD3ε+ T cell subsets demonstrated a significant increase in the frequency and absolute cell count of both IL-17A+ γδ and αβ CD4+ T cell subsets in the recovery phase of aDSS colitis." (PMID 30876876, 2019). "As STAT1 is a critical regulator of Th1/Th17 differentiation, we further investigated its role in the ability of CD4+ T cells to induce colitis." (PMID 30796216, 2019). "We measured IFN-γ- and IL-17A-producing colitis LP CD4+ T cells using AMPK agonist, 5-Aminoimidazole-4-carboxamide ribonucleotide (AICAR) and antagonist, Compound C (C.C.)." (PMID 31417110, 2019). "In the CD45RBhi CD4+ T cell transfer model of colitis, large amounts of CD11c+ DCs expressing activation marker OX40 ligand (OX40L) are found in the MLN, and transferred T cells create aggregates with CD11c+ DCs in the lamina propria." (PMID 31886308, 2019). "In conclusion, DHA exerts an anti-colitis effect by regulating the Th/Treg balance, and the mechanism is closely related to the induction of activated CD4+ T cell apoptosis via the regulation of HO-1." (PMID 31284478, 2019). "Both in blood and MLNs, a significantly lower percentage of CD4+ cells within the lymphocyte gate was observed in mice with acute DSS colitis (p = 0.033 and p < 0.001 respectively compared to control mice)." (PMID 31296924, 2019).
colitis (continued). "LP CD4+ T cells of colitis SCID mice (colitis LP CD4+ T cells) injected with CD4+ CD45RBhigh T cells were isolated and stimulated with PMA plus ionomycin mixed with BBR or not." (PMID 31417110, 2019). "In this study, the production of IL-6, IL-17, and IL-10 by mesenteric lymph node cells as well as STAT4 phosphorylation in splenic CD4+ T cells were decreased in colitis mice supplemented with AHCC®." (PMID 31930148, 2019). "Next, we assessed the BBR effects on SCID colitis mouse model which injected with CD4+CD45RBhigh T cells." (PMID 31417110, 2019). "In MLNs, a significant higher percentage of CD4+Foxp3+ Tregs was observed within the lymphocyte gate already in the acute colitis phase (p < 0.001)." (PMID 31296924, 2019). "WT B cells decreased histologic inflammation in a CD4+ and B cell co-transfer colitis model with significantly less protection by either PI3KδD910A or Il10−/− B cells." (PMID 31546615, 2019). "Using a naïve CD4+ T cells adoptive transfer colitis model, we found that VD did have a marked influence on T cells differentiation with an obvious suppression of Th1/Th17 cells and enhancement of Tregs." (PMID 30792721, 2019). "These mice developed a mild form of colitis comparable to that of Rag1−/− mice adoptively transferred with WT CD4+ T cells." (PMID 31379813, 2019). "Mice receiving Asc−/− CD4+ T cells had more severe colitis as highlighted by higher clinical and histological scores, and a markedly higher number of activated T cells infiltrating the colonic LP." (PMID 31379813, 2019). "A 89Zr-labeled CD4+ cDb has been evaluated in naïve 23 and colitis 62 mice as well as a model of hematopoietic stem cell transplantation." (PMID 31754392, 2019). "To determine the role of Tregs in the immunomodulation caused by rBmaCys treatment in DSS-induced colitis mice, we analyzed the percent frequency of CD3+CD4+CD25+FoxP3+ Tregs in the colon, spleen, and mesenteric lymph nodes (MLNs)." (PMID 31683524, 2019). "While colitis alone manifested in patients with numbers of CD4 T lymphocytes ranging between 184 and 252 per μL of blood, a more significant decline (to 118 or 64 CD4/μL) resulted in the occurrence of another complication, retinitis or pneumonitis." (PMID 31690039, 2019). "T cell transfer colitis in lymphopenic mice is driven by CD4+ T cells which get activated, expand and differentiate in response to commensal bacterial antigens and innate immune signals delivered by DCs." (PMID 31276514, 2019). "To investigate the role of STAT1 signaling in T-cell driven colitis, we adoptively transferred unfractionated WT or Stat1−/− CD4+ T cells into Il10rb−/−Rag1−/− mice." (PMID 30796216, 2019). "Next, we evaluated the effect of MT-1303 and an anti-mTNF-α mAb on colitis induced by adoptive transfer of CD4+CD45RBhigh T cells." (PMID 31805144, 2019). "Animal models on the role of T-cells in colitis development have also largely focused on CD4+ T-cells." (PMID 30936879, 2019). "We have also shown that Asc−/− Tregs have no defect in their suppressive capacity in vivo as they were able to restrain the proliferation of WT CD4+ T cells in our colitis model." (PMID 31379813, 2019). "CD4+FoxP3+ regulatory T cells (Tregs), in addition to Th1 and Th17 cells, also play an important role in development of colitis." (PMID 31805144, 2019). "We therefore focused on AMPK and attempted to reveal its immunological effects, particularly in relation to colitis LP CD4+ T cells, data on which are scarce." (PMID 31417110, 2019). "We found differential expression of IL-1 in B6 vs. F1 mice and antibody blockade of IL-1 rescued mice on the B6-background from onset of colitis by reducing CD4 T cell numbers and avoiding generation of Th17/Th1 and Th1 cells." (PMID 30653608, 2019). "As expected, the phosphorylation state of AMPK at Thr172 (p-AMPK) expressions was significantly increased in BBR-treated colitis LP CD4+ T cells." (PMID 31417110, 2019).
colitis (continued). "We also demonstrate that IL-21 neutralization only is efficacious in models with CD4 T cell-driven colitis and primarily affects homing of calprotectin-positive cells." (PMID 29849593, 2018). "Despite, these intriguing findings, future studies are needed to demonstrate that the protective role of DUSP6 in colitis is intrinsic to CD4+ T cells." (PMID 30429852, 2018). "Mice with conditional deletion of HDAC2 in CD4+ T cells have elevated IL-17 expression and severe colitis." (PMID 30375383, 2018). "In this study, we show that proliferation of colitis-inducing CD4+CD62Lhigh T cells is prevented by DX5+NKT cells." (PMID 30364054, 2018). "As a key role for CD4+ cells and Ifng in DSS‐induced colitis has been previously shown, we repeated this experiment using Ifng−/− mice and neutralising CD4+ antibodies to determine their contribution to the phenotype." (PMID 29603746, 2018). "It has been previously shown that immunoregulatory DX5+NKT cells are able to prevent colitis induced by CD4+CD62Lhigh T lymphocytes in a SCID mouse model." (PMID 30364054, 2018). "In oxazolone colitis, the significant increased % of CD4+LAP+ cells in uninvolved vs. involved tissue was confirmed also by confocal microscopy." (PMID 30425718, 2018). "In both murine models of colitis and experimental autoimmune encephalomyelitis, CD4 T cells only expressing the STAT4β isoform drive exacerbated disease as compared to cells expressing the STAT4α isoform." (PMID 29910812, 2018). "Activation of STAT3 in adaptive immune cells such as CD4+ T cells contributes for the development of colitis in a mouse model of CD." (PMID 29075900, 2018). "The ability of BI119 to prevent colitis in vivo was assessed in the CD4+CD45RBhigh T cell transfer model." (PMID 30405600, 2018). "A popular approach to generating tolerogenic DC has been the combination dexamethasone/vitamin D3 conditioning of bone marrow DC, and these DC were shown to suppress colitis in the CD4+ CD25− colitogenic T-cell transfer SCID model." (PMID 29774025, 2018). "Our findings suggest that the decrease in the number of colitis-inducing CD4+CD62Lhigh T cells as well as their proliferation capacity in the presence of DX5+NKT cells is principally executed through FasL-Fas interaction." (PMID 30364054, 2018). "Tbx21-deficient CD4 T cells, isolated from BALB/c mice, were unable to induce colitis in a SCID adoptive transfer model of IBD." (PMID 29910812, 2018). "Collectively, these data confirmed that DX5+NKT cells inhibit proliferation of colitis-inducing CD4+CD62Lhigh cells by induction of apoptosis." (PMID 30364054, 2018). "To assess the function of TRIM28 in naive T cells in vivo, we used a T-cell transfer colitis model in which Rag1−/− mice were injected with CD4+CD45RBhi naive T cells isolated from WT or Trim28−/− mice." (PMID 29651155, 2018). "In co-housed mice the acquisition of Rickenellaceae by Nod2+/+ mice was associated with increased CD4+ LAP+ Foxp3− proportion and less severe colitis." (PMID 30250234, 2018). "Taken together, these data suggest that the combined loss of iNKT cells and dysregulated IFNγ production can induce a decrease in protective Foxp3+CD25+CD4+ T cells during DSS-induced colitis." (PMID 30333822, 2018). "To test this, we assessed PGE2 concentration in colon explants of WT untreated mice or Rag1−/− mice undergoing colitis induced by adoptive transfer of effector CD4+ cells." (PMID 30619314, 2018). "In patients with either proctitis or left-sided colitis, the percentage of CD4+Foxp3+ cells was significantly higher in involved tissue than in uninvolved tissue." (PMID 30425718, 2018). "On the other hand, protective effects of IL17A were ascribed to an IL17A-mediated attenuation of T-bet and IFNγ expression, leading to a more aggressive colitis upon transfer of IL17A−/− CD4 T cells into lymphopenic hosts." (PMID 29416538, 2018). "Co-administration of WT tTreg cells effectively suppressed the induction of colitis by CD4+CD25− T cells." (PMID 29386580, 2018).
colitis (continued). "According to previous reports, rutin, a flavonoid present in IA extract, has been shown to exert intestinal anti-inflammatory effects in experimental models in the CD4+ CD62L+ T cell transfer model of colitis." (PMID 30545135, 2018). "On the contrary, in a T-cell transfer colitis model, RA was required for the induction of CD4+ T-cell differentiation and expansion into the Th1 lineage." (PMID 30081517, 2018). "Transfer of NK1.1−NKG2D+CD4+ T cells delayed the onset of DSS-induced colitis and the protective effect was dependent on TGF-β." (PMID 29910814, 2018). "We have also identified that deficiency of paracrine mPGES1-driven PGE2 exacerbates T cell-driven colitis by selectively decreasing CD4+FoxP3+ cells in the mLN, with a concomitant increase of total number of CD4+ infiltration in the cLP." (PMID 30619314, 2018). "Co-transfer of Treg cells prevented colitis by reducing the expansion of activated IFNγ-producing and IL-17-producing CD4+ T cells." (PMID 29549257, 2018). "In this context, CYP26B1, which is responsible for the catabolism of RA, has been shown to regulate the differentiation and function of CD4 T cells during experimental colitis, driving the cells towards an inflammatory profile." (PMID 30158832, 2018). "We found that enrichment of Rikenella and Alistipes (Rikenellaceae) in Nod2−/− mice at 8 weeks of age reared separately was associated with increased proportion of CD4+ LAP+ Foxp3− cells and less severe TNBS-colitis." (PMID 30250234, 2018). "Then, effects of alpinetin and TCDD on DNMT-1 level in colons of colitis mice and CD4+ T cells were examined." (PMID 30166541, 2018). "Two separate studies demonstrated accumulation of NKG2D+CD4+ T cells in colon LP in a CD4+ T cell transfer-induced colitis model and disease amelioration after treatment with blocking α-NKG2D antibodies." (PMID 29910814, 2018). "In the T cell transfer colitis model, the introduction of PTPN2 deficient CD4+ T cells resulted in an almost 3-fold increase in the frequency of IFNγ producers and a 2-fold increase in the frequency of IFNγ+ IL17+ double producers." (PMID 30429852, 2018). "Given the importance for IFNγ and ILC3 in innate immune cell-mediated acute intestinal inflammation, we next assessed their role in the CD4 T cell transfer model of colitis." (PMID 29416538, 2018). "Specifically, PTPN11 CD4+ T cell deficient mice display enhanced TH1 immunity and aggravated colitis, but the deficiency inhibited the development of AOM-DSS colitis-associated carcinoma." (PMID 30429852, 2018). "Collectively, we demonstrate that targeting exacerbated IL17 secretion in an IFNγ-deficient environment has disease-limiting properties in the CD4 T cell transfer mouse model of colitis." (PMID 29416538, 2018). "These immunologic defects result in spontaneous and lethal colitis that is preventable with CD4+ T cell depletion, Treg cell transplantation, or antibiotic therapy." (PMID 29382851, 2018). "Increased IL-6 production by the lamina propria and CD4+ T cells has been reported in experimental colitis models." (PMID 30289911, 2018). "The pathologic role of IL-21 was examined in murine models of T cell-dependent and T cell-independent colitis, either with a neutralizing monoclonal antibody against IL-21 or with the transfer of CD4+CD45RBhighIL-21R−/− T cells." (PMID 29849593, 2018). "As well, Rag2−/− mice receiving CD4+CD45RBhighIL-21R−/− T cells developed less severe colitis compared to Rag2−/− mice receiving CD4+CD45RBhighIL-21R+/+ T cells." (PMID 29849593, 2018). "Using a T cell dependent model of colitis, we show that deficient production or sensing of PGE2 reduces the colitogenic potential of transferred CD4+ T cells." (PMID 30619314, 2018). "Consistently with our results of the current study, LSA treatment suppressed the differentiation of naive CD4 T cells into Th1 subsets which have been considered in the mouse colitis model." (PMID 29977172, 2018).
colitis (continued). "A normal course of colitis development was observed in Rag2KO mice receiving naïve CD4+ T cells from Cnb1CD11c mice." (PMID 29549257, 2018). "While a significantly reduced proportion of αv−/− Treg in the colon LP was still apparent at harvest, they represented an average 5.4% of the colonic CD4+ T cell population versus 2.2% in the first curative colitis experiment." (PMID 29535709, 2018). "Because IL-21 is reported to be produced by both human and mouse Th17 cells and since Th17 cells have been shown to be involved in adoptive transfer colitis, we initially focused on the CD4+CD25− T cell transfer model of colitis." (PMID 29849593, 2018). "CD4 T cell expansion in peripheral blood as a sign of colitis onset and body weight were monitored throughout the experiment." (PMID 29416538, 2018). "The protective effects of GLP on colitis induced by DSS were associated with an increase in B cells but a decrease in T cells, mainly a decrease in 17A-producing CD4+ T-LPLs, and a decrease in the production of IL-17A and IL-4 in LP." (PMID 29888292, 2018). "In our study, we observed less severe colitis in Rag2 k.o. mice transferred with CD45RBhighIL-21R−/− CD4+ T cells compared with mice transferred with CD45RBhighIL-21R+/+ CD4+ T cells." (PMID 29849593, 2018). "For instance, in trinitrobenzene sulfonic acid (TNBS)-induced murine colitis, RARα agonist injection skewed the lamina propria CD4+ T cells toward a Th2 phenotype." (PMID 30081517, 2018). "Upon occurrence of clinical signs of colitis, CD4 T cells were isolated from the colonic lamina propria (LP) for subsequent analysis of cytokine responses." (PMID 29416538, 2018). "As predicted, DSS‐treated mice transfused with NK1.1− CD4+ NKG2D+ cells delayed the onset of colitis and decreased disease severity." (PMID 28224733, 2017). "IL-10 induced differentiation of CD4 T cells into type 1 regulatory T (Tr1) cells and prevented colitis induced in severe combined immunodeficient (SCID) mice by pathogenic CD4 + CD45RB (high) splenic T cells." (PMID 28455817, 2017). "The specific role of CD9 in IBD was further dissected by transfer of CD4+ CD45RBhi naive T cells into the Rag1−/− mouse colitis model." (PMID 29312336, 2017). "This analysis revealed an impaired proliferative capacity of Bcl-3-overexpressing CD4+ T cells compared with control CD4+ T cells upon stimulation, an impairment that can explain the failure of these cells to induce transferred colitis." (PMID 28452361, 2017). "Here we show that a mutation in Ccdc88b protects mice against experimental intestinal colitis, both in the DSS-colitis and CD4 T cells transfer models." (PMID 29030607, 2017). "Although the disease activity index of colitis was increased in CD4+ T/RAG KO mice, the administration of DCPAB and HPAB attenuated colitis development." (PMID 28169371, 2017). "GPR15 mediates the colon localization of CD4+ CD25+ effector and regulatory cells to the colon and has been implicated in colitis in models of infectious and autoimmune intestinal inflammation." (PMID 28936214, 2017). "In DSS-induced colitis model, the pretreatment of mice with Hsp65-LL increased the CD4+Foxp3+ cell frequency in the spleen when compared to naïve mice after 3 days of colitis induction." (PMID 28194152, 2017). "The frequency of NK1.1−CD4+NKG2D+ cells decreased in inflamed colons, whereas more NK1.1+CD4+NKG2D+ cells infiltrated into colons of mice with DSS‐induced colitis." (PMID 28224733, 2017). "Adoptive transfer of BMDC exposed to helminth homogenates, resulted in CD4+ T cell IL-10 mediated disease suppression in an experimental model of colitis." (PMID 29073139, 2017). "Adoptive transfer of NK1.1− CD4+ NKG2D+ T cells into DSS‐treated mice suppressed the onset of colitis dependent on TGF‐β." (PMID 28224733, 2017).